VHL (von Hippel-Lindau tumor suppressor)
Diseases named in the same sentence as VHL in open-access papers (continued):
Sharing a sentence is not in itself a finding about the gene and the disease.
clear cell renal cell carcinoma (continued). "The VHL gene is responsible for inherited familial VHL cancer syndrome, and mutations of the VHL gene, accompanied by loss of heterozygosity, are also found in 70–80% of sporadic clear cell renal cell carcinoma (ccRCC)." (PMID 34586601, 2021). "PBRM1 mutations have been associated with clear cell renal carcinoma, but in our BM data this mutation appeared in a broad spectrum of cases and infrequently with VHL mutations, suggesting it may have a broader role in promoting metastasis." (PMID 34830758, 2021). "Mutations in the von Hippel Lindau (VHL) gene are responsible for the VHL disease, an autosomal dominant cancer syndrome that predisposes to various benign and malignant tumors, including clear cell Renal Cell Carcinoma (ccRCC), hemangioblastoma or pheochromocytoma." (PMID 33137104, 2020). "With that in mind, inactivation of VHL, including mutations and other modifications such as methylation, is associated with various illnesses such as clear-cell renal cell carcinoma (ccRCC) due to aberrant VHL/HIF axis and may also affects human phenotypes." (PMID 33109235, 2020). "VHL mutation is the most common mutation in clear cell renal cell carcinoma (ccRCC)." (PMID 33372609, 2020). "In clear cell renal cell carcinoma (ccRCC), miR-30c-2-3p and miR-30a-3p are downregulated in von Hippel-Lindau (VHL)-deficient cancer tissues, and both miRNAs specifically bind to hypoxia inducible factor-2α (HIF2A) and inhibit the expression of its transcripts." (PMID 32977589, 2020). "In addition, tumours like clear cell renal carcinomas (ccRCC) where VHL is mutated arise as a potential target for β-blockers." (PMID 31296894, 2019). "VHL mutation, whether inherited or sporadic is frequently implicated in the tumorigenesis of renal clear cell carcinoma." (PMID 31200666, 2019). "Furthermore certain types of VHL mutations such as loss-of-functions mutation VHLR200W that causes Chuvash polycythemia or other VHL-associated tumors such as clear cell renal carcinoma or pheochromocytomas have been discussed." (PMID 30214643, 2018). "Clear cell renal cell carcinomas frequently bear a mutated Von Hippel-Lindau (VHL) gene." (PMID 29732003, 2018). "In clear-cell renal cell carcinoma (ccRCC), loss of von Hippel-Lindau (VHL) tumour suppressor gene and reduced oxygen tension promote stabilisation of hypoxia-inducible factor (HIF) family of transcription factors, which promote changes in the expression of genes that contribute to oncogenesis." (PMID 29463811, 2018). "VHL mutation is characteristic for renal clear cell carcinoma." (PMID 29560117, 2018). "In contrast, Gerlinger and colleagues analyzed ten clear cell renal carcinomas and report that chromosome 3p loss and von Hippel–Lindau gene (VHL) aberrations were the only ubiquitous events, whereas 73–75% of identified driver aberrations were of subclonal origin." (PMID 28937589, 2017). "Mutations in VHL have been linked to clear cell renal cancer, but the molecular mechanisms involved remain unclear." (PMID 29229903, 2017). "More recently, we showed that tumors from clear cell renal cell carcinoma (ccRCC) patients displaying VHL biallelic inactivation (i.e., loss of function) exhibit a significant increase in PD-L1 expression as compared to ccRCC tumors carrying one VHL wild-type allele." (PMID 27917371, 2016). "In clear cell renal cell carcinoma (ccRCC), but few other cancers, somatic loss-of-function mutations, chromosomal aberrations or promoter hypermethylation lead to decreased activity of von Hippel–Lindau tumour suppressor protein (pVHL)." (PMID 27774982, 2016). "The tumor-suppressing activity of HIF-1α is strongly indicated by the genetic evidence that focal, homozygous deletions of HIF1A gene are found in many VHL-deficient renal clear-cell carcinoma cell lines and the functional evidence that HIF-1α inhibits cell proliferation and tumor growth." (PMID 25893706, 2015).
clear cell renal cell carcinoma (continued). "The most notable example of a genetic alteration driving HIF activity is in clear cell renal cell carcinoma (ccRCC), which has a high incidence of VHL loss-of-function due to either mutation or epigenetic silencing, which leads to high HIF activity even under non-hypoxic conditions." (PMID 25326682, 2014). "This discrepancy stands in contrast to recent whole genome characterization of clear cell renal carcinomas, which have somatic mutations in the VHL gene in >80% of samples, focal deletion by loss of chromosome 3p26.1 in >90%, or epigenetic silencing by promoter methylation in 7%." (PMID 25589003, 2014). "However, by contrast, it has been reported that there is a loss of TMEM115 expression in renal clear cell carcinomas and other VHL-deficient tumors." (PMID 24806965, 2014). "For renal clear cell carcinoma, the most common type of kidney cancer, TCGA identified epigenetic silencing of the tumor suppressor VHL in about 7 % of the tumors, which was mutually exclusive with VHL mutations." (PMID 25473433, 2014). "The most direct link between genetic events that predispose to cancer and activation of the HIF pathway is observed in tumors associated with inactivation of the von Hippel-Lindau (VHL) tumor suppressor gene, particularly VHL-associated clear-cell renal cell carcinoma (CCRCC)." (PMID 20652061, 2010). "In addition the kidney cluster is enriched for clear-cell renal carcinoma (P-value < 0.002) which has been shown to be caused by loss of VHL." (PMID 20017941, 2009). "Somatic VHL mutations are also common in sporadic clear cell renal carcinoma and hemangioblastomas." (PMID 17598890, 2007). "Moreover, blocking β2-adrenergic receptors has shown therapeutic benefits in clear cell renal cell carcinoma (ccRCC) with the VHL gene’s loss of function by reducing inflammation and oxidative stress, thus possibly explaining the observed effects on RCC-Shaw and Caki-1 cell lines." (PMID 40005133, 2025). "The histologic differential diagnosis between intracranial hemangioblastoma (HB) and metastatic clear cell renal cell carcinoma may be challenging, especially considering that both tumors exhibit clear cell morphology and can be associated with vHL mutation and/or Von Hippel-Lindau syndrome." (PMID 39807616, 2025). "Additionally, VHL mutation-mediated SALL4 overexpression promoted clear cell renal cell carcinoma (ccRCC) cell proliferation, colony formation, cell cycle progression, migration, invasion, tumorigenicity, and tumor vascularization through modulating Akt/GSK-3β axis and VEGF-A expression." (PMID 37525212, 2023). "Previous studies have shown that mutations in the tumor suppressor gene von Hippel-Lindau (VHL) can result in the overproduction of reactive oxygen species (ROS) and chronic inflammation and are a significant predisposing factor for the development of clear-cell renal cell carcinoma (ccRCC)." (PMID 34257811, 2021). "Furthermore, NICI expression is regulated by the von Hippel–Lindau (VHL) tumor suppressor and is highly expressed in clear cell renal cell carcinoma (ccRCC), where SLC2A3 expression is associated with patient prognosis, implying an important role for the HIF/NICI/SLC2A3 axis in this malignancy." (PMID 31690629, 2020). "However, normoxic elevation and activation of HIF can be caused either by loss/inactivating mutations in VHL (occurring in most clear cell renal cell carcinomas) or by oncogenic pathways that increase the transcription, translation, and/or activity of the HIF-α subunit in non-RCC tumors." (PMID 31076951, 2019). "Inactivation of the VHL (Von Hippel Lindau) tumour suppressor has long been recognised as necessary for the pathogenesis of clear cell renal cancer (ccRCC); however, the molecular mechanisms underlying transformation and the requirement for additional genetic hits remain unclear." (PMID 29229903, 2017).
clear cell renal cell carcinoma (continued). "Similarly, it should be investigated whether altered glycogen metabolism plays any role on the development of renal clear cell carcinomas driven by VHL mutations." (PMID 26882899, 2016). "The loss of chromosome 3p and the inactivation of the tumor suppressor gene von Hippel-Lindau (VHL) were identified in clear cell renal cell carcinomas (ccRCC) over three decades ago." (PMID 41602827, 2026). "In the majority of renal clear cell carcinoma cases, the activity of the von Hippel-Lindau tumor suppressor (VHL) protein is lost due to genetic or epigenetic changes in the cancer cell genome." (PMID 40011447, 2025). "Clear cell renal cell carcinoma (ccRCC), the most common malignancy with metastasis to the thyroid gland (>20%), is characterized by high frequency of VHL gene inactivation (49–89%), which is rare in primary thyroid tumors." (PMID 40989257, 2025). "Inactivation of the VHL gene stabilizes HIF2α, which drives clear-cell renal cell carcinoma (ccRCC)." (PMID 40178040, 2025). "Regarding the pathogenesis of VHL syndrome complicated by thyroid nodules, studies have shown that VHL gene alterations, as a core molecular marker of metastatic clear cell renal cell carcinoma (ccRCC), have a key value in the diagnosis of thyroid nodules." (PMID 40989257, 2025). "Biallelic mutation of the VHL ubiquitin ligase leads to constitutive activation of hypoxia inducible factors HIF1A and HIF2A and is generally a truncal event in clear cell renal carcinoma." (PMID 41102155, 2025). "Clear cell renal cell carcinoma progression is driven by a positive feedback loop between PDGFRβ signaling and inactive VHL-triggered histone lactylation." (PMID 39968078, 2025). "In clear cell renal cell carcinoma (ccRCC), where HIF-1α/VEGF-α signaling driven by VHL inactivation is a hallmark, the biological effects of zinc are not fully understood." (PMID 41220925, 2025). "This short report describes the role of the von Hippel–Lindau (VHL) tumor suppressor gene and Lon protease in clear cell renal carcinoma (ccRCC) development, focusing on inflammation and reactive oxygen species (ROS) accumulation in kidney cells." (PMID 39451551, 2024). "In contrast, the VHL substrate transcription factor zinc fingers and homeoboxes 2 (ZHX2) have been identified as the oncogenic drivers in VHL-deficient clear cell renal cell carcinoma (RCC)." (PMID 39850947, 2024). "This work shows that PHD1 and VHL also inhibit Beclin1 and autophagy initiation, with dysregulation leading to clear-cell renal cell carcinoma progression." (PMID 38360997, 2024). "While many genes function as drivers in several cancer types, some drivers are mutated at high frequencies only in specific tumors, such as VHL in clear cell renal cell carcinoma and FGFR3 in bladder cancer." (PMID 38890488, 2024). "Examples include the breast cancer gene 1 (BRCA1) in ovarian and breast cancer, the Von Hippel–Lindau tumor suppressor (VHL) in clear renal cell carcinoma and the O-6-methylguanine-DNA methyltransferase (MGMT) repair gene in glioblastoma (GB)." (PMID 38473745, 2024). "Inactivation of the VHL tumor suppressor gene is the signature initiating event in the most common form of kidney cancer, clear cell renal cell carcinoma (ccRCC)." (PMID 39365820, 2024). "The VHL substrate transcription factor zinc fingers and homeoboxes 2 (ZHX2) have been identified as an oncogenic driver in VHL-deficient clear cell renal cell carcinoma (RCC)." (PMID 39850947, 2024). "Clear cell renal cell carcinoma (ccRCC) represents the most common form of kidney cancer and is typified by biallelic inactivation of the von Hippel-Lindau (VHL) tumour suppressor gene." (PMID 39282259, 2024). "On the other hand, males suffer from a higher tumor burden of central nervous system hemangioblastomas, while females show faster growth rates of VHL-related clear cell renal cell carcinomas." (PMID 38481600, 2024).
clear cell renal cell carcinoma (continued). "The VHL gene is a tumour suppressor gene that plays an important role in regulating the hypoxia pathway in the sporadic pathogenesis of clear-cell renal carcinoma." (PMID 39336594, 2024). "Somatic mutations of the Von Hippel–Lindau tumor suppressor gene (VHL) are commonly detected in sporadic renal cell carcinoma (RCC), with clear-cell renal cell carcinoma (ccRCC) being the most common subtype." (PMID 38360997, 2024). "By studying the single cell morphological and genetic characteristics of CTC from patients with VHL-positive clear cell renal carcinoma, we found that cytomorphology had 100% specificity but much lower sensitivity." (PMID 37444476, 2023). "Clear-cell renal cell carcinoma (ccRCC or KIRC) is the most common type of kidney cancer, which is best described by the loss of the chr3p locus, which contains the Von Hippel–Lindau tumor suppressor (VHL) gene." (PMID 37047552, 2023). "In 70–90% of patients with clear cell renal cell carcinoma, the VHL gene is inactivated, resulting in significantly increased hypoxia-inducing factor (HIF) levels in the cancer cells in the normoxic state." (PMID 37749329, 2023). "Clear cell renal cell carcinoma (ccRCC) is the most common histological subtype of renal cancer, and inactivation of the VHL tumor suppressor gene is found in almost all cases of hereditary and sporadic ccRCCs." (PMID 36980176, 2023). "Clear cell renal cell carcinoma (ccRCC) is a hypervascular tumor that is characterized by bi-allelic inactivation of the VHL tumor suppressor gene and mTOR signalling pathway hyperactivation." (PMID 37047421, 2023). "In the kidney, HIF-1α is expressed in tubular epithelial cells, and HIF-2α in glomerular and peritubular cells, as well as VHL-defective clear cell renal cancer cells, which derive from the proximal tubule." (PMID 37206967, 2023). "Clear cell renal cell carcinoma (ccRCC), the most common form of kidney cancer, is typically initiated by inactivation of the von Hippel Lindau (VHL) gene, which results in the constitutive activation of the hypoxia inducible factors, HIF-1α and HIF-2α." (PMID 36097192, 2022). "In the majority of clear cell renal cell carcinomas (ccRCCs), the tumor suppressor VHL is inactivated." (PMID 36077607, 2022). "The inactivation of von Hippel–Lindau (VHL) is critical for clear cell renal cell carcinoma (ccRCC) and VHL syndrome." (PMID 35159281, 2022). "Advanced research showed, at least in clear cell renal cell carcinoma (ccRCC), CD70 upregulation is driven by HIF, which ought to be hydrolyzed by pVHL (VHL protein), and the story started with Von Hippel–Lindau gene (VHL) mutations in ccRCC." (PMID 35978433, 2022). "Inactivation of the VHL tumor suppressor gene is the signature initiating event in clear cell renal cell carcinoma (ccRCC), which is the most common form of kidney cancer." (PMID 35357972, 2022). "Shallow deletion of VHL was prevalent in kidney clear cell carcinoma (76.7%), but substantially less common in other cancer types collectively (23.7%)." (PMID 35664333, 2022). "Most clear cell renal carcinomas have a large histologic subtype, genetic or epigenetic von Hippel-Lindau (VHL)." (PMID 36447689, 2022). "VHL is the substrate recognition component of the multi-subunit E3 ligase complex comprising Elongin B, Elongin C, Cullin-2, Rbx1, and VHL, and is the tumor suppressor of clear cell renal cell carcinoma (ccRCC)." (PMID 36140200, 2022). "Among the identified potential tumor suppressor genes, DAG1 was co-deleted with the Von Hippel Lindau (VHL) tumor suppressor gene in clear cell renal cell carcinoma." (PMID 36499305, 2022). "The molecular profiling of vascular cells in clear cell renal carcinomas analyzed by single-cell sequencing exhibited increased hypoxia signaling, supporting that the VHL-Hypoxia-inducible factor (HIF) pathway is dysregulated in these tumors." (PMID 35874919, 2022).
clear cell renal cell carcinoma (continued). "In clear cell renal cell carcinoma, 80% of cases have biallelic inactivation of the VHL gene, leading to constitutive activation of both HIF1α and HIF2α." (PMID 34353313, 2021). "VHL and PBRM1 are major genes that cause mutations in more than 40% of clear cell renal cell carcinoma, and SETD2 and PTEN, which are quite frequent, are genes that cause both copy number loss and mutation." (PMID 33905431, 2021). "Clear cell renal cell carcinoma (ccRCC) is characterized by the inactivation of the von Hippel–Lindau (VHL) gene." (PMID 34976818, 2021). "Inactivation of the von Hippel-Lindau tumor suppressor (pVHL) is the best-known oncogenic event in clear cell renal cell carcinoma (ccRCC)." (PMID 34631715, 2021). "Clear cell renal cell carcinoma (ccRCC) carrying wild-type Von Hippel–Lindau (VHL) tumor suppressor are more invasive and of high morbidity." (PMID 34760693, 2021). "Von Hippel Lindau (VHL) inactivation, which is common in clear cell renal cell carcinoma (ccRCC), leads directly to the disruption of oxygen homoeostasis." (PMID 33799686, 2021). "Inactivation of the von Hippel–Lindau tumor-suppressor gene (VHL) is found in most clear cell renal cell carcinomas (ccRCCs)." (PMID 34575959, 2021). "Loss of function mutations of VHL protein, a key ECV component in renal clear cell carcinoma (RCC) results in elevated HIF1α levels." (PMID 33603169, 2021). "VHL-HIFs signal is a important role in the development of clear cell renal cell carcinoma (ccRCC), and the tyrosine kinase inhibitors (TKIs) that target the VHL substrate HIF signal have showed treating benefit in patients with advanced ccRCC." (PMID 32382017, 2020). "Although VHL alterations are established markers of clear cell renal cell carcinomas, their role is much less clear in other kidney tumor entities." (PMID 32076485, 2020). "Genetic inactivation of VHL leads to stabilization of HIF-1α/HIF-2α and is associated with clear cell renal cell carcinoma (ccRCC) initiation and progression." (PMID 32807776, 2020). "Inactivation of the VHL gene occurs in most hereditary von Hippel-Lindau disease and sporadic clear-cell renal carcinomas." (PMID 32989053, 2020). "Loss of von Hippel-Lindau protein pVHL function promotes VHL diseases, including sporadic and inherited clear cell Renal Cell Carcinoma (ccRCC)." (PMID 33137104, 2020). "This leads to the upregulation of MMP14 in kidney clear cell carcinoma in patients with deletion of VHL." (PMID 31200666, 2019). "In clear cell renal cancer, concomitant loss of PBRM1 rescues VHL-induced replication stress, maintaining cellular fitness and allowing proliferation." (PMID 31615521, 2019). "The blood of 30 patients with clear cell renal cell carcinoma was treated by ISET® for CRC isolation, cytopathology and single-cell VHL mutations analysis, performed blindly and compared to VHL mutations of corresponding tumor tissues and leukocytes." (PMID 29732003, 2018). "The von Hippel-Lindau (VHL) tumor suppressor gene is inactivated in the vast majority of human clear cell renal carcinomas." (PMID 29435132, 2018). "All the CCC and 83,2% (104/125) of the CRC-UMF were found to carry the same VHL mutation identified in the corresponding tumorous tissue, validating cytopathological identification of CCC in patients with clear cell renal cell carcinoma." (PMID 29732003, 2018). "In VHL-defective tumors, like renal clear cell carcinoma, the HIF transcriptional program is constitutively activated." (PMID 29560117, 2018). "Clear cell renal cell carcinomas (ccRCC) harbor mutations in the VHL gene, whereas papillary RCC (pRCC) have a functional VHL." (PMID 30555801, 2018). "In the present study, we observed that levels of 5hmC in the promoter region of Von Hippel-Lindau (VHL) were lower in 97 samples of renal clear cell carcinoma tissue than in matched adjacent benign tissues." (PMID 28969028, 2017).